LINC00460 (long independently transcribed non-coding RNA 460)
Diseases named in the same sentence as LINC00460 in open-access papers (continued):
Sharing a sentence is not in itself a finding about the gene and the disease.
cancer (31 papers, 2017 to 2025). A tumor composed of atypical neoplastic, often pleomorphic cells that invade other tissues. "Of four lncRNA biomarkers in the DNAMeFourLncSig, the dysregulated expression of LINC00460 has recently been reported to affect cell proliferation and apoptosis and are closely associated with cancer development and metastasis." (PMID 33869232, 2021). "In these models, LINC00460 sponging activity and its association with cancer-related processes such as increase in proliferation, epithelial to mesenchymal transition (EMT), migration, invasion and metastasis is well described." (PMID 33912452, 2021). "Since LINC00460 is primarily localized in the cytoplasm, some studies have shown that LINC00460 associates with a number of biomolecules, such as TFs, mRNAs, miRNAs and RBPs, to affect cancer development." (PMID 31429766, 2019). "According to one study, increased levels of LINC00460 were connected with cancer-related molecular pathways such as EMT and other inflammatory response pathways." (PMID 37733767, 2023). "Studies have shown that LINC00460 knockdown significantly suppressed cancer cell progression at the G1 phase of the cell cycle." (PMID 35906593, 2022). "Recently, aberrant expression of LINC00460 has been considered an independent prognostic factor in diverse cancers." (PMID 35906593, 2022). "LINC00460 has been reported to participate in many kinds of malignancies and promotes cancer progressions." (PMID 35912013, 2022). "A related study suggested that LINC00460 is a potential biomarker related to outcomes in malignant tumors, which provides critical insights into the targeting of FRLRS in predicting ccRCC." (PMID 35242188, 2022). "LINC00460 has also been shown to be a promising biomarker for diagnosis as well as prognostic evaluation in cancer patients." (PMID 35906593, 2022). "LINC00460 is located on chromosome 13q33.2 and is transcribed into a 935 bp transcript; this lncRNA has recently been reported in several cancers." (PMID 33526059, 2021). "Taken together with previous findings reported in the field, this data suggests a relevant role for LINC00460 in clinical cancer biology." (PMID 33912452, 2021). "Although, some kinds of molecular mechanism of LINC00460 in cancer progression have been reported, the potential mechanism in regulating CRC progression needs further explored." (PMID 33526059, 2021). "Given that migration and invasion are essential in cancer metastasis, we investigated the role of LINC00460 in CRC metastasis in vivo." (PMID 33526059, 2021). "Similar LINC00460 sponging and cancer-related mechanisms across distinct tumors are described in several reports." (PMID 33912452, 2021). "With the use of this strategy, LINC00460, the most frequently epigenetically activated, was identified and further verified in the Cancer Cell Line Encyclopedia and Gene Expression Omnibus databases." (PMID 31632435, 2019). "Existing literatures show that LINC00460 exerts its role in the aggressiveness of several cancers." (PMID 35096063, 2022). "However, LINC00460 is expressed in a broad range of cancer types, making it less specific in distinguishing the origin of tumors." (PMID 35906593, 2022). "LINC00460 is a promising candidate potential target for cancer therapy for HNSCC." (PMID 35846149, 2022). "Moreover, these provide support for the potential of LINC00460 as a novel biomarker and as a therapeutic target for cancers." (PMID 35906593, 2022). "Recently, many studies have analyzed DElncRNAs in normal and LUAD tissues and have shown that LINC00460 is closely related to the progression of many types of diseases including cancer, which may become a new therapeutic strategy for EGFR-mutant LUAD." (PMID 36091160, 2022). "LINC00460 has been reported to inhibit apoptosis in various cancers." (PMID 35906593, 2022). "The LINC00460 role in clinical cancer features has also been studied." (PMID 33912452, 2021).
cancer (continued). "The previously reported mechanisms of LINC00460 in cancers are highly variable and contradictory." (PMID 31429766, 2019). "Additionally, we measured linc00460 expression in multiple cancer celllines, the results indicated that linc00460 was overexpressed in many digestivesystem cancers." (PMID 28939763, 2017). "Similarly, a previous study showed dual prognostic roles of LINC00460 in different cancer types." (PMID 37260772, 2023). "LINC00460 overexpression is significantly related to high risk of death in eight different tumors, analyzed in a single model (CESC, GBM, HNSC, KIRC, LGG, LUAD, PAAD and SARC) (log2HR>1; p<0.05), and with high risk of relapse in four cancers (KIRC, LUAD, READ and SARC) (log2HR>1; p<0.05)." (PMID 33912452, 2021). "Among NSCLC tissues, Linc00460 is overexpressed, and hindering Linc00460 expression affects the expression of EMT-related proteins, thereby inhibiting cancer cell invasion and metastasis." (PMID 38152110, 2023). "LINC00460 and LINC00525 were upregulated in LUAD, which improved the levels of FAM111B and ZWINT via hsa-mir-338 sponge, thus promoting the occurrence of cancer." (PMID 35406786, 2022). "Second, further analysis has identified seven NET-related genes, including NIFK, LINC00460, NUTF2, and LINC02454, some of which are potentially predictive biomarkers for human cancers." (PMID 36225931, 2022). "LINC00460 and PRDX1 are promising candidate prognostic predictors and potential targets for cancer therapy for HNSCC." (PMID 31429766, 2019). "Our findings reveal that inhibiting CASC19 expression significantly impedes cancer cell migration, whereas the knockdown of LINC00460 does not produce a similar effect." (PMID 38740871, 2024). "LINC00460 and PRDX1 may serve as biomarkers for accurate prognostic prediction and as potential targets for cancer therapy in HNSCC patients." (PMID 31429766, 2019). "After demonstrating that LINC00460 is significantly related to aggressiveness markers in different tumors, we then aimed to know if its deregulation is also related to overall survival (OS) and relapse free survival (RFS) in these cancers, using the TCGA cohorts." (PMID 33912452, 2021). "Indeed, multiple lines of evidence suggest that LINC00460 can modulate cell proliferation, cell death, migration and invasion and EMT, through its sponging activity and targeting various key transcripts in several cancer types." (PMID 33912452, 2021).
LINC00460 also shares sentences with these, for which no sentence is quoted: non-small cell lung carcinoma (5 papers); nasopharyngeal carcinoma (4); ovarian carcinoma (3); bladder cancer (2); colon adenocarcinoma (2); renal cell carcinoma (2); acute myeloid leukemia (1); breast invasive carcinoma (1); cutaneous squamous cell carcinoma (1); gastric adenocarcinoma (1); glioblastoma (1); hepatoblastoma (1); laryngeal squamous cell carcinoma (1); lung squamous cell carcinoma (1); metastatic tumors (1); neuroblastoma (1); rectum adenocarcinoma (1); skin cancer (1); thyroid carcinoma (1).